L3MBTL3 (L3MBTL histone methyl-lysine binding protein 3)
Description:
Is a negative regulator of Notch target genes expression, required for RBPJ-mediated transcriptional repression. It recruits KDM1A to Notch-responsive elements and promotes KDM1A-mediated H3K4me demethylation. Involved in the regulation of ubiquitin-dependent degradation of a set of methylated non-histone proteins, including SOX2, DNMT1 and E2F1. It acts as an adapter recruiting the CRL4-DCAF5 E3 ubiquitin ligase complex to methylated target proteins. Required for normal maturation of myeloid progenitor cells (By similarity).
Synonyms: KIAA1798; MBT1; MBT-1
Tractability: Small molecule: a structure with a bound ligand is known; a high-quality ligand is known. PROTAC: UniProt records ubiquitination sites on it; ubiquitination databases record sites on it; its protein half-life has been measured; a small molecule that binds it is known.
Target class: Methyl-lysine/arginine binding protein; MBT domain; Epigenetic regulator; Reader
Chemical probes: UNC1215 (high quality)
Gene: Protein-coding gene on chromosome 6 (130,013,699 to 130,141,449, forward strand). Ensembl gene ENSG00000198945.
Subcellular location: Nucleus
Subcellular location (Human Protein Atlas): Nucleoli; Nucleoplasm; Cytokinetic bridge; Primary cilium; Vesicles
Gene Ontology:
Molecular function: chromatin binding; identical protein binding; methylation-dependent protein binding; protein binding; histone binding; zinc ion binding
Biological process: negative regulation of DNA-templated transcription; negative regulation of transcription initiation-coupled chromatin remodeling; positive regulation of ubiquitin-dependent protein catabolic process; regulation of DNA-templated transcription; regulation of ubiquitin-dependent protein catabolic process
Cellular component: nucleolus; nucleoplasm; nucleus
Genetic constraint (gnomAD): Loss-of-function variants: 9 observed, 48.17 expected, observed/expected ratio (o/e) 0.19, 90% interval 0.11 to 0.33. The upper end of that interval is the gene's LOEUF score, 0.33, which puts it in group 1 of 6, group 1 being the genes least tolerant of losing a copy. Missense variants: 508 observed, 603.1 expected, observed/expected ratio (o/e) 0.84, 90% interval 0.78 to 0.91. Synonymous variants: 208 observed, 211.73 expected, observed/expected ratio (o/e) 0.98, 90% interval 0.88 to 1.1.
Homologues: Orthologues: chimpanzee L3MBTL3 (99% identical), macaque L3MBTL3 (99% identical), pig L3MBTL3 (97% identical), rabbit L3MBTL3 (97% identical), dog L3MBTL3 (97% identical), guinea pig L3MBTL3 (91% identical), rat L3mbtl3 (90% identical), mouse L3mbtl3 (89% identical), zebrafish l3mbtl3 (53% identical), Drosophila melanogaster Scm (16% identical), Drosophila melanogaster l(3)mbt (16% identical), Drosophila melanogaster Sfmbt (14% identical), and 2 more. Paralogues in human: L3MBTL4 (39% identical), L3MBTL1 (39% identical), SCML2 (17% identical), SCMH1 (16% identical), SFMBT1 (16% identical), SFMBT2 (16% identical), L3MBTL2 (14% identical), PHC1 (13% identical), MBTD1 (13% identical), PHC2 (12% identical), SAMD11 (12% identical), PHC3 (11% identical), and 6 more.
Diseases named in the same sentence as L3MBTL3 in open-access papers:
L3MBTL3 is named in the same sentence as 27 diseases in open-access papers, as found by Europe PMC text mining. Sharing a sentence is not in itself a finding about the gene and the disease. The quoted sentences say what the papers report.
medulloblastoma (8 papers, 2010 to 2024). A malignant, invasive embryonal neoplasm arising from the cerebellum. "L3mbtl3 mutations are found in medulloblastoma, and L3mbtl3 is further implicated in prostate cancers and breast cancers." (PMID 38396925, 2024). "Single- and double-strand deletions of L3MBTL2 and L3MBTL3 were found in medulloblastoma whereas L3MBTL4 has mutations or deletions in breast cancer." (PMID 39231972, 2024). "Human L3MBTL3 is mutated in medulloblastoma and is further implicated in other pathological disorders such as multiple sclerosis, insulin resistance, prostate cancer, and breast cancer." (PMID 36335117, 2022). "L3MBTL3 is mutated in medulloblastoma and is further implicated in other pathological disorders such as multiple sclerosis, insulin resistance, prostate cancer and breast cancer." (PMID 29691401, 2018). "A recent study reported focal hemi- and homozygous deletions of L3MBTL2 and L3MBTL3 in medulloblastoma." (PMID 20698951, 2010). "Moreover, L3MBTL3 is deleted in some human medulloblastoma cell lines whose malignant phenotypes become attenuated upon re-expression of L3MBTL3." (PMID 28855394, 2017). "It will be important to determine whether the role of LIN-61 in DSB repair is conserved in human MBT proteins and whether MBT mutated tumours, such as medulloblastomas with mutations in L3MBTL2, L3MBTL3 or SCML2, are HR deficient as they too may prove responsive to treatment with PARP inhibitors." (PMID 23505385, 2013).
prostate carcinoma (7 papers, 2018 to 2025). A carcinoma that arises from epithelial cells of the prostate gland. "The most noteworthy gene is L3MBTL3 (PIP = 1) which has not previously been linked to prostate cancer but has been reported to be associated with height, type 2 diabetes, and body mass index, all suspected risk factors of prostate cancer." (PMID 38887957, 2024).
breast carcinoma (5 papers, 2023 to 2024). "However, L3MBTL3 expression was downregulated in breast cancer (BRCA), cervical cancer (CESC), kidney chromophobe (KICH), Pheochromocytoma and Paraganglioma (PCPG), thyroid cancer (THCA), and uterine corpus endometrial carcinoma (UCEC)." (PMID 38201555, 2023). "All four genes were near (<500 kb) breast cancer SNPs previously identified by GWAS11, and two genes (L3MBTL3 and RCCD1) also were reported by prior breast cancer TWAS 14,15,32." (PMID 36690614, 2023).
malignant brain tumor (5 papers, 2017 to 2023). "During the purification of DNMT1 protein complexes, we have also noticed the presence of peptides derived from L3MBTL3, a protein that contains the three tandem repeated malignant brain tumor (MBT) domain." (PMID 29691401, 2018). "Bovine L3MBTL3 protein isoforms expressed in GC and the endometrial cell line possesses three malignant brain tumor (MBT) repeat domains (MBT-1: M268-K336; MBT-2: M375-Y442; MBT-3: M479-P543), C2HC zinc finger domain (G557-S586) and a sterile alpha motif domain (SAM; S706-K770)." (PMID 29100496, 2017). "The protein identified as L3MBTL3 (Lethal malignant brain tumor-like 3), which also goes by the name MBT1, is a transcriptional repressor that belongs to the MBT (malignant brain tumor) family and contains MBT domains." (PMID 38201555, 2023). "The malignant brain tumor (MBT) family is a large family with L3MBTL1, L3MBTL2, L3MBTL3, L3MBTL4, and other members." (PMID 38201555, 2023). "L3MBTL3, also known as MBT1, acts as a member of the MBT (malignant brain tumor) family." (PMID 36747531, 2023).
anemia (2 papers, 2018 to 2024). A reduction in the number of red blood cells, the amount of hemoglobin, and/or the volume of packed red blood cells. "Mouse null mutation of the L3MBTL3 (MBT-1−/−) gene was reported to impair the maturation of hematopoietic system, reduce the expression of genomic imprinted CDK inhibitor p57Kip2 gene, and cause anemia and late embryonic lethality around E17.5-E19.547." (PMID 29691401, 2018).
brain tumor (2 papers, 2016 to 2024). "The methylated lysine residue is specifically recognized by L3MBTL3, a methyl-lysine reader that contains the malignant brain tumor domain, to target the methylated proteins for proteolysis by the CRL4DCAF5 ubiquitin ligase complex." (PMID 38396925, 2024). "Human L3MBTL3 is a putative methyl-lysine reader because it contains the malignant brain tumor (MBT) domain with three MBT-repeated motifs." (PMID 38396925, 2024).
lung carcinoma (2 papers, 2023 to 2024). "We also used siRNA-mediated silencing of L3mbtl3 in human lung carcinoma H1299 cells with two representative siRNAs." (PMID 38346162, 2024). "For instance, cervical cancer (CESC), lung cancer (LUAD), and GC (STAD) with high expression of L3MBTL3 were associated with poorer prognosis, while the opposite was observed in cholangiocellular cancer (CHOL) and kidney cancer (KIRC)." (PMID 38201555, 2023).
acute leukemia (1 paper, 2016). A clonal (malignant) hematopoietic disorder with an acute onset, affecting the bone marrow and the peripheral blood. "The gene L3MBTL3 encodes a Polycomb group protein that maintains the transcriptionally repressive state of genes and is frequently deleted in several forms of acute leukemia, including AML." (PMID 27386562, 2016).
breast tumor (1 paper, 2010). "L3MBTL1, L3MBTL2 and L3MBTL3 paralogs were not targeted by deletion in our breast tumor set." (PMID 20698951, 2010).
gastric cancer (1 paper, 2023). A primary or metastatic malignant neoplasm involving the stomach. "Recent research has linked lethal malignant brain tumor-like 3 (L3MBTL3) to cancer aggressiveness and a dismal prognosis, but its function in gastric cancer (GC) is unclear." (PMID 38201555, 2023). "However, the association and potential mechanism of L3MBTL3 involved in gastric cancer have not been reported." (PMID 38201555, 2023).
cancer (3 papers, 2023 to 2024). A tumor composed of atypical neoplastic, often pleomorphic cells that invade other tissues. "Further investigation is required to clarify the alterations of L3MBTL3 and substrate sensitivity in various cancer cells." (PMID 38346162, 2024). "Our studies found that the levels of L3MBTL3 protein are differentially expressed in various cancer cell lines and that T47D cells express relatively low levels of L3MBTL3 protein among the cell lines we analyzed." (PMID 38346162, 2024). "A survival analysis in pan-cancer also revealed that the expression of L3MBTL3 has different or even opposite effects on the prognosis of different tumors." (PMID 38201555, 2023). "Altogether, these gene enrichment studies illustrate that L3MBTL3 is important in the immune response of GC, as well as the invasion of cancer cells via cell adhesion pathways." (PMID 38201555, 2023). "To facilitate our analysis, we determined the relative abundance of L3MBTL3 mRNA in a TCGA pan-cancer sample." (PMID 38201555, 2023). "In this study, we utilized data from the TCGA database to investigate the gene expression levels of L3MBTL3 in various human cancer tissues compared with normal tissues." (PMID 38201555, 2023). "The L3MBTL3, PLA2G7, KIAA1614, and C3orf33 genes were implicated in DNA repair, cell proliferation, apoptosis, and the cell cycle, and may be involved in the development of cancers." (PMID 39839768, 2024). "Considering that cancer cells may enhance immune cell polarization through chemokines and chemokine receptors, the present research established a correlation between the expression of L3MBTL3 and chemokines and receptors based on the TISIDB database." (PMID 38201555, 2023). "The ROC curve analysis of the TCGA data demonstrated that L3MBTL3 expression had a remarkable predictive capacity to distinguish cancer tissues from non-cancer tissues, with an AUC of 0.805 (95% CI = 0.738–0.872)." (PMID 38201555, 2023). "Notably, we discovered that L3MBTL3 mRNA levels were remarkably higher in GC, as well as many other cancers, as opposed to non-cancer tissues." (PMID 38201555, 2023).
tumor (2 papers, 2013 to 2023). "Results like these highlighted the possible function of L3MBTL3 as a predictive and diagnostic marker in GC tumor growth." (PMID 38201555, 2023). "The biological role of the lethal malignant brain tumor-like 3 (L3MBTL3) has been investigated in human malignancies, but its involvement in GC is not well understood." (PMID 38201555, 2023). "In addition, the correlations between L3MBTL3 and tumor-infiltrating immune cells were determined based on the TIMER database; the results showed that L3MBTL3 was associated with the immune infiltration of macrophages and their polarization from M1 to M2." (PMID 38201555, 2023). "Additionally, the upregulation of L3MBTL3 expression in tumor tissues compared with normal tissues was also observed in two other independent datasets: GSE19826 and GSE65801." (PMID 38201555, 2023). "Furthermore, our findings suggested a possible function for L3MBTL3 in the regulation of the tumor immune microenvironment of GC." (PMID 38201555, 2023). "L3MBTL3 expression was found to be upregulated or downregulated in different tumors, suggesting that it may have varying roles in different tumor types." (PMID 38201555, 2023).
kidney disease (1 paper, 2024). "Moreover, it was shown that increased whole blood expression of TP53INP1 and L3MBTL3 was associated with an increased risk of kidney disease; TWAS, SMR, and colocalization analysis corroborated this finding." (PMID 39193563, 2024).
L3MBTL3 also shares sentences with these, for which no sentence is quoted: multiple sclerosis (4 papers); Insulin resistance (3); atopic asthma (1); bladder cancer (1); cervical cancer (1); colon cancer (1); esophageal cancer (1); kidney cancer (1); Obesity (1); Pheochromocytoma and Paraganglioma (1); skin cancer (1); thyroid cancer (1); type 2 diabetes (1); uterine corpus endometrial carcinoma (1).